BBS9 (Bardet-Biedl syndrome 9)
Description:
The BBSome complex is thought to function as a coat complex required for sorting of specific membrane proteins to the primary cilia. The BBSome complex is required for ciliogenesis but is dispensable for centriolar satellite function. This ciliogenic function is mediated in part by the Rab8 GDP/GTP exchange factor, which localizes to the basal body and contacts the BBSome. Rab8(GTP) enters the primary cilium and promotes extension of the ciliary membrane. Firstly the BBSome associates with the ciliary membrane and binds to RAB3IP/Rabin8, the guanosyl exchange factor (GEF) for Rab8 and then the Rab8-GTP localizes to the cilium and promotes docking and fusion of carrier vesicles to the base of the ciliary membrane. Required for proper BBSome complex assembly and its ciliary localization.
Synonyms: PTHB1; B1; C18; D1
Tractability: Antibody: its Gene Ontology location is reachable by antibodies, with medium confidence. PROTAC: ubiquitination databases record sites on it.
Gene: Protein-coding gene on chromosome 7 (33,109,557 to 33,877,180, forward strand). Ensembl gene ENSG00000122507.
Subcellular location: Cytoplasm, cytoskeleton, microtubule organizing center, centrosome; Cell projection, cilium membrane; Cytoplasm; Cytoplasm, cytoskeleton, microtubule organizing center, centrosome, centriolar satellite
Subcellular location (Human Protein Atlas): Flagellar centriole; Mid piece; Primary cilium; Primary cilium tip; Primary cilium transition zone; Principal piece; Acrosome; Cytosol; Equatorial segment; Nucleoplasm; Vesicles
Pathways (Reactome):
Organelle biogenesis and maintenance: BBSome-mediated cargo-targeting to cilium
Gene Ontology:
Molecular function: protein binding
Biological process: protein localization to cilium; cilium assembly; fat cell differentiation
Cellular component: BBSome; centriolar satellite; ciliary membrane; ciliary tip; ciliary transition zone; cilium; cytosol; pericentriolar material; membrane; centrosome; cytoplasm
Genetic constraint (gnomAD): Loss-of-function variants: 80 observed, 100.48 expected, observed/expected ratio (o/e) 0.8, 90% interval 0.66 to 0.96. The upper end of that interval is the gene's LOEUF score, 0.96, which puts it in group 4 of 6, group 1 being the genes least tolerant of losing a copy. Missense variants: 890 observed, 990.71 expected, observed/expected ratio (o/e) 0.9, 90% interval 0.85 to 0.95. Synonymous variants: 345 observed, 357.29 expected, observed/expected ratio (o/e) 0.97, 90% interval 0.88 to 1.06.
Gene-disease validity (ClinGen):
ClinGen rates the evidence that BBS9 causes each of these diseases.
BBS9-related ciliopathy (autosomal recessive): Definitive. Any ciliopathy caused by variants in the BBS9 gene.
Homologues: Orthologues: chimpanzee BBS9 (99% identical), macaque BBS9 (98% identical), pig BBS9 (93% identical), dog BBS9 (92% identical), rabbit BBS9 (91% identical), guinea pig BBS9 (89% identical), mouse Bbs9 (88% identical), rat Bbs9 (87% identical), tropical clawed frog bbs9 (70% identical), zebrafish bbs9 (60% identical), Drosophila melanogaster BBS9 (29% identical), Caenorhabditis elegans bbs-9 (20% identical).